CCND1 (cyclin D1)
Diseases named in the same sentence as CCND1 in open-access papers (continued):
Sharing a sentence is not in itself a finding about the gene and the disease.
prostate carcinoma (continued). "Collectively, these results indicated that there was low expression of CCND1, CDK4 and TWIST1; high expression of SNAI1, SNAI2, and CDH1 was correlated with good prognosis of prostate cancer patients." (PMID 31060254, 2019). "It has been demonstrated that cyclin D1 and CDK4 play central roles in the regulation of proliferation of prostate cancer." (PMID 31060254, 2019). "The most common actionable genetic alterations in the prostate cancer cohort included: 6 DNA damage repair altered tumors (55%), 4 PTEN (36%), 4 AR receptor (36%), 3 CCND1 (27%), 2 CDKN2A (18%), and 2 FGF family altered tumors (18%)." (PMID 30551737, 2018). "As c‐Myc and cyclin D1 genes are positive regulators of cell proliferation, we evaluated the effect of TRPM4 knockdown in prostate cancer cell proliferation through MTS and BrdU incorporation assays." (PMID 28614631, 2018). "Cyclin D1: PI3K/Akt inhibitors and metformin have both been shown to reduce the level of cyclin D1, an inducer of cell cycle progression and prostate cancer cell proliferation." (PMID 30533337, 2018). "In various cancers, including prostate cancer and ovarian carcinoma, upregulation of USP2 leads to an increase in the levels of deubiquitinated substrates such as fatty acid synthase, MDM2, cyclin D1 and Aurora-A." (PMID 29449607, 2018). "Ki-67, cyclin D1 and CDK4 were over expressed in prostate cancer, concomitant with significant down regulation of p21 in prostate cancer." (PMID 28852180, 2017). "PlncRNA-1 is an oncogene that regulates the cell cycle, cyclin-D1 and EMT in prostate cancer cells through the TGF-β1 pathway." (PMID 28212533, 2017). "The cyclin D1/MCM8 interaction is required for Rb phosphorylation and S-phase entry in prostate cancer cells." (PMID 29285216, 2017). "In prostate cancer PC-3 cells, silencing ANO1 reduced the expression of cyclin D1 (CCND1), cyclin A2 (CCNA2), CDK1 and CDK2." (PMID 27732935, 2016). "Hono also caused cell cycle arrest by decreasing the expression of cell cycle-related proteins, such as cyclin D1, CDK4 and CDK6 in PC-3 prostate cancer cells." (PMID 27074557, 2016). "In LNCaP, a human androgen-dependent prostate cancer cell line, PGZ also inhibited cyclin D1 expression and the activation of both p38 MAPK and NFκB." (PMID 27973395, 2016). "On the other hand, in regard to proliferation, Slug reportedly downregulates cyclin D1 expression to inhibit the proliferation of PC3 and DU145 prostate cancer cells." (PMID 27385093, 2016). "Up-regulated BCL2, CCND1 and WNT3A which promote tumorigenic features, are the main targets of miR-15a and miR-16-1 in prostate cancer." (PMID 25743273, 2015). "Because it is known that one gene can be targeted by several miRNAs and that cyclin D1 is a key regulator of the cell cycle G1/S transition, it is not surprising that CCND1 has been suggested to be a target of more than one miRNA in prostate cancer." (PMID 26129688, 2015). "Using this approach, we confirm that four previously reported prognostic markers, PTEN, SMAD4, CCND1 and SPP1, can predict lethal outcome of human prostate cancer." (PMID 25075204, 2014). "This suggests that the miRNAs not only co-regulate and suppress PTEN expression in prostate cancer cells, but also coordinately affect the key components of PI3K/Akt and cyclin D1." (PMID 24098737, 2013). "Cyclin D1 is an important downstream component regulated by PI3K/Akt signaling and is usually overexpressed in prostate cancer." (PMID 24098737, 2013). "Src inhibitor treatment inhibits proliferation of prostate cancer cells through β-catenin, ERK1/2, GSK3β-mediated cyclin D1, and c-Myc regulation." (PMID 24349321, 2013). "Overall, these findings link ATF3-mediated CCND1/2 activation to its SUMOylation and thereby imply this modification plays a functional role in CCND1/2 activation by ATF3 in prostate cancer PC3 and DU145 cells." (PMID 23591848, 2013).
prostate carcinoma (continued). "Our results found that four miRNAs, which include miR-19b, miR-23b, miR-26a and miR-92a, promote cell proliferation of prostate cancer in vitro by targeting regulation of PTEN and its downstream signals, PI3K/Akt and cyclin D1." (PMID 24098737, 2013). "MiR-370 upregulated the cell-cycle regulator cyclin D1 by directly targeting the FOXO1 3′-UTR, demonstrating that FOXO1 is regulated by miR-370 in prostate cancer cells." (PMID 23029264, 2012). "In advanced prostate cancer, for instance, miR-15a and miR-16 are significantly downregulated, whereas the expression of BCL2, CCND1 and WNT3A is concomitantly upregulated." (PMID 22583478, 2012). "The list of up and downregulated genes in VEGFA165 tumours include known genes involved in neoplasia (e.g. S100A8 involved in leukaemia; S100A9 in prostate carcinoma; BCL9, CCND1 and CTNNB1)." (PMID 22045186, 2011). "For instance, constitutive activation of Cyclin D1 (CCND1) has been shown to promote Rb phosphorylation and cellular growth in numerous cancers including prostate cancer." (PMID 20948989, 2010). "Cell cycle arrest at the G1 phase is caused by reducing the binding of cyclin E to cdk2 and increasing the binding of cyclin D1 to WAF1/p21 and KIP1/p27, which inactivates the cyclin‐cdk complexes active in the G0/G1 phase of the cell cycle and induces apoptosis in human prostate carcinoma cells." (PMID 40255557, 2025). "The results showed that circFOXK2 and CCND1 are expressed significantly higher in a number of cancer types we tested including colorectal cancer (CRC), esophageal squamous cell carcinoma (ESCC), and prostate cancer (PRAD)." (PMID 40233410, 2025). "Our results showed lower expression of Wnt pathway-related proteins—β-catenin, Fzd8, Wnt5a and cyclin D1—in prostate cancer compared to BPH tissues, but the differences were not statistically significant." (PMID 41465498, 2025). "In androgen‐sensitive LNCaP and androgen‐insensitive DU145 human prostate carcinoma cells, upregulation of the protein expression of INK4c/p18, INK4a/p16, KIP1/p27, and WAF1/p21, and downmodulation of cdk 2, 4, and 6, cyclin D1, and cyclin E result in programmed cell death." (PMID 40255557, 2025). "Similarly, a study on prostate cancer showed that Piezo1 downregulation inhibited the expression of Cyclin D1 and CDK4, hindering the assembly of the Cyclin D1-CDK4 complex and thus impeding cell cycle progression in prostate cancer cells." (PMID 38690080, 2024). "In prostate cancer cells, curcumin downregulates miR-21, leading to an increase in phosphatase and tensin homolog gene (PTEN) and programmed cell death protein 4 gene (PDCD4) (target genes for miR-21), and a decrease in proliferation markers such as cyclin D1." (PMID 39445208, 2024). "Thus, AE significantly downregulated β-catenin, the crucial protein of the Wnt/β-catenin signaling pathway, and expression of its downstream target proteins such as cyclin D1 and c-myc, in DU145 prostate cancer cells." (PMID 38348349, 2023). "It has been reported that genistein may inhibit the proliferation of prostate cancer cells through regulating the expression of ER-akt, PSA, p21, Cyclin D1, CDK4, etc.." (PMID 36794010, 2023). "For the AMPK-independent pathway, metformin inhibits the cell cycle in the G0/G1 phase without inducing apoptosis or decreasing the cyclin D1 protein level in prostate cancer cells." (PMID 37213670, 2023). "Formononetin can induce prostate cancer transformation through the ERK1/2 MAPK-Bax pathway, which can also inhibit the G1 cell cycle by inactivating Akt/cyclin D1/CDK4, making it exhibit inhibitory activity on human prostate cancer cells both in vivo and in vitro." (PMID 35594510, 2022). "Taken together, these findings indicate that RASAL2 plays an oncogenic role in prostate cancer and may promote PCa tumorigenesis through PI3K/AKT signalling and cyclin D1 expression." (PMID 35668070, 2022).
prostate carcinoma (continued). "Similarly, SOX18 can enhance cell migration and proliferation in both in vitro and in vivo models of prostate cancer by promoting the transcription of the pro-growth factors TCF1, c-Myc, and cyclin D1." (PMID 36620216, 2022). "It was known that AR amplification sensitizes prostate cancers to low levels of androgen, that PI3K (PIK3CA/B) and Wnt (RSPO2) pathways can bypass the AR function for cell proliferation, and that CCND1 regulates the cell cycle; therefore, all five genes are involved in mCRPC." (PMID 34439974, 2021). "In addition, the expression of cyclin D1, PCNA, and p21 is modified leading to proliferation inhibition of distinct prostate cancer cell lines." (PMID 33937075, 2021). "Several reports have shown that Cdk4 hyperactivity is associated with the overexpression of cyclin D and several cancers showing elevated levels of cyclin D1 expression including breast (60% of patients), CRC (40% of patients), and prostate cancers (20% of patients)." (PMID 32847114, 2020). "To further elucidate the mechanism how HNF1B influences the cell cycle, we re‐explored and analysed the RNA‐seq data, and focused on Cyclin D1, which a key regulator of cell cycle (G1‐ phase) for both normal and tumour cells, is negatively regulated by HNF1B in prostate cancer cells." (PMID 33174391, 2020). "Additionally, in prostate cancer,SNHG7 promotes cell proliferation via cyclin D1 by modulatingmiR-503.Further, SNHG7 sponges miR-34a and induces over-expression ofGALNT7, which in turn results in the progression of colo-rectalcancer." (PMID 32453338, 2020). "Re‐introduction of SMAD6 restored Cyclin D1 expression and cell proliferation, which supports the hypothesis that HNF1B inhibits prostate cancer cell proliferation by direct repression of SMAD6." (PMID 33174391, 2020). "Ubiquitin-proteasome is involved in prostate cancer in various ways by modulating prostate cancer-related genes/proteins such as androgen receptor, heat shock protein (HSP) 90, cyclin-dependent kinase inhibitor p27, cyclin D1, and PTEN." (PMID 30972102, 2019). "Inactivation of PTEN and SMAD4 and activation of cyclin D1 and SPP1 promote prostate cancer." (PMID 31551414, 2019). "The combination of PTEN/SMAD4 does not predict risk for prostate cancer recurrence, but the PTEN/SMAD4/CCND1/SPP1 four-gene signature does." (PMID 31551414, 2019). "Besides, because anticarcinogenic properties of naringenin have been reported in diverse malignant tumors prostate cancer pathway consisting of eight proteins was found: AKT1, MAPK1, IGF1R, AR, CCND1, INS, PIK3CA, IGF1." (PMID 30918758, 2019). "PTS induced G1 arrest and efficiently blocked cyclin D1 expression in both bone metastasis-derived PC-3 and brain metastasis-derived DU-145 cells, indicating the potential of PTS on inhibiting metastasis in prostate cancers." (PMID 30555320, 2018). "Soy milk digestion extract (daizein, glycitein, genistein) might inhibit the proliferation of in vitro human prostate cancer cells by regulating the expression of ERβ, PSA, p21, Cyclin D1 and CDK4 in an estrogen receptor (ER)-dependent manner." (PMID 29844867, 2018). "Furthermore, we show an impact of miR-17, -20a/b and -106a/b on the expression of their target gene CCND1 as well as on growth behavior and apoptosis of LNCaP cells to confirm the impact of miRNA deregulation during NETD of prostate cancer cells." (PMID 30001402, 2018). "The median expression of CCND1 was 15% of HS prostate cancer cells (range 0–70%, not shown) and 20% of cancer cells in CRPC tissues (range 0–80%)." (PMID 27191720, 2016). "In LNCaP prostate cancer cells, reduced expression of SAM68 altered the expression of an important subset of genes involved in proliferation and apoptosis, including Bcl2L1, Clusterin, cdk2, cdk3, p16INK4, cyclin D1, Par-4, EGF and IGF-1." (PMID 25944080, 2015).
prostate carcinoma (continued). "Because cyclin D1 regulates the activity of CDK4/6, we treated PC cell lines with the CDK4/6 inhibitor PD0332991 at different concentrations and measured the effect on prostate cancer cell growth." (PMID 26129688, 2015). "These collective data suggested that ATF3 overexpression plays an important role in promoting cell growth and colony formation of prostate cancer PC3 and DU145 cells by modulating CCND1/2 activity and SUMOylation is involved in and essential for this promotion." (PMID 23591848, 2013). "Because SUMOylation is involved in ATF3-mediated CCND1/2 activation and CCND activity is required for cell cycle progression, we next investigated the potential role of SUMOylation of ATF3 in proliferation of prostate cancer cells." (PMID 23591848, 2013). "In human prostate cancer cell lines transfected with the fat-1 gene, proliferation was inhibited through a reduction in GSK-3β phosphorylation and a subsequent downregulation of β-catenin and cyclin D1." (PMID 21655218, 2011). "Downregulation of cyclin D1 in response to metformin has been demonstrated in LNCaP prostate cancer cells but the importance of CDK inhibitors was not addressed in this study." (PMID 19046439, 2008). "The present finding that prostate cancer cells frequently exhibit cytoplasmic cyclin D1 is novel, but not without precedent." (PMID 17375037, 2007). "Regardless of the site, the mechanism(s) by which cyclin D1 accumulates in prostate cancer cells remains to be discerned." (PMID 17375037, 2007). "Cyclin D1 status was characterised using immunohistochemistry in 38 non-neoplastic prostate samples, 138 primary human prostate carcinomas, and three lymph node metastatic specimens." (PMID 17375037, 2007). "Consistent with the negative feedback model, full-length cyclin D1 markedly inhibited cell cycle progression in AR dependent (but not AR negative) prostate cancer cells." (PMID 16863592, 2006). "According to these results, chitosan salicylaldehyde/CuFe2O4 may have a greater impact than chitosan salicylaldehyde in reducing the expression of PI3K, AKT, mTOR, and Cyclin D1, which in turn prevents the survival and proliferation of PC3 prostate cancer cells." (PMID 39900661, 2025). "In prostate cancer p73 has been shown to be a negative modulator of cyclin D1." (PMID 31167517, 2019). "Furthermore, the mRNA levels of C-Myc, Cyclin D1, CD44 and CD133 were upregulated by FZD6 depletion, which indicated that FZD6 negatively regulates Wnt signaling and inhibits the stemness of prostate cancer." (PMID 29867083, 2018). "Thus, AMPA inhibits prostate cancer metastasis through suppressing cyclin D1 expression, implicating that AMPA may be used for prevention of prostate cancer metastasis." (PMID 26840261, 2016). "TMPRSS4 induced Slug, an epithelial-mesenchymal transition (EMT)-inducing transcription factor, and cyclin D1 through activation of AP-1, composed of c-Jun and activating transcription factor (ATF)-2, which resulted in enhanced invasion and proliferation of PC3 prostate cancer cells." (PMID 27385093, 2016). "Finally, when prostate cancer cell lines were treated with the CDK4/6 inhibitor PD0332991, the cell lines responded to the treatment according to miR-193b expression/methylation status and cyclin D1 levels." (PMID 26129688, 2015). "In addition, we found that BMP-2, a 4HPR target with antiangiogenic activity, decreased prostate cancer cell proliferation, migration and invasion by down-regulating the pathway described involving AKT phosphorylation, β-catenin stability and cyclin D1 expression." (PMID 20537156, 2010). "Moreover, CCND1 is known to further negatively regulate the AR function, not only by directly binding to AR to inhibit transactivation of AR, but also by attenuating AR-induced upregulation of Klk4 in prostate cancer." (PMID 29249975, 2017).
prostate carcinoma (continued). "In PC-3 prostate cancer cells, CAPE decreased cyclin D1 and cyclin E, but not p21 protein expression, while cyanidin-3-O-β-glucopyranoside induced p21 protein expression in the DU-145 and LNCaP prostate cancer cell lines." (PMID 30823649, 2019).
melanoma (326 papers, 1996 to 2026). A malignant, usually aggressive tumor composed of atypical, neoplastic melanocytes. "Cyclin D1 promotes uncontrolled cell proliferation, a hallmark of cancer, and its amplification has been reported in up to 90% of melanoma cases." (PMID 39948552, 2025). "The frequency of mutations in the CCND1 gene encoding cyclin D1 depends on the melanoma subtype and ranges from 19 to 80%." (PMID 36674631, 2023). "Downregulation of miR-206, miR-143, or miR-106b inhibits CCND1 via affecting G1 cell cycle causing decrease in melanoma cells invasion or migration." (PMID 36224606, 2022). "In the present study, we investigated the association between CCND1 amplification and the tumor immune microenvironment in melanoma using data from the TCGA cohort." (PMID 35844619, 2022). "The CCND1 (BCL1) gene, encoding cyclin D1 is a key protein for cell cycle regulation (G1 to S phase transition), and also plays a major role in BRAFi resistance mechanisms in melanoma cells." (PMID 36077374, 2022). "The BRAF mutation is the most common mutant gene in melanoma and co-occurred with CCND1 amplification in 0.33% (1/302), 1.91% (7/367), and 1.14% (4/350) of tumor samples from the Geneplus, TCGA, and MSKCC cohorts, respectively." (PMID 35844619, 2022). "Melanoma with CCND1 amplification is an independent genomic subtype associated with a poor prognosis, an immunosuppressive TME, activated oxidative and lipid metabolism, and down-regulated angiogenesis." (PMID 35844619, 2022). "It is worth noticing that NRAS or BRAF mutation are frequent and associated with melanoma subtypes together with cyclin D1 and other factors." (PMID 33917849, 2021). "The loss of the CDKN2A locus also cooperates with Cyclin D1 in promoting resistance to BRAF inhibitors in melanoma." (PMID 34066022, 2021). "CCND1 amplification was associated with a decreased overall survival in a cohort of melanoma patients as well as in patients with solid tumors." (PMID 33923996, 2021). "The melanoma-risk CCND1 rs1485993*T allele was positively associated with decreased Breslow thickness, passing false discovery, and borderline associated with absence of mitoses." (PMID 34898573, 2021). "The melanoma-risk alleles of other SNPs in the CCND1 gene neighborhood (rs11604821*G and rs11263498*T) were nominally associated with both decreased Breslow thickness and absence of mitoses." (PMID 34898573, 2021). "CCND1 amplifications have been found in 17% of BRAF-driven melanomas (11% in melanoma) and have been associated with poor prognosis and intrinsic resistance to BRAFi-based targeted therapy." (PMID 34066022, 2021). "CCND1 encodes the cyclin D1 protein, which is complexed with cyclin-dependent kinases (CDKs) and regulates the cell cycle to induce cell migration and angiogenesis, linked to melanoma and metastatic progression." (PMID 33428680, 2021). "We performed a stratified analysis with the melanoma (n = 231) and bladder carcinoma patients (n = 111) and observed a similar association between CCND1 amplification with a shorter OS." (PMID 32903763, 2020). "Regions of CCND1 amplification had few—sometimes zero—mutations at high variant allele fraction in acral melanomas, in contrast to later CCND1 amplifications in cutaneous melanomas, in which hundreds to thousands of mutations typically predated amplification." (PMID 32025007, 2020). "PPP6C encodes for the catalytic subunit of PP6 protein phosphatase complex, acting as a negative regulator of the melanoma oncogene CCND1 and as the major phosphatase of the Aurora kinase, and was found to be mutated in 9% of melanoma samples." (PMID 29156643, 2017). "Second, reducing cyclin D1 expression through by deletion of a single allele inhibits melanoma genesis." (PMID 27977682, 2016). "Dysregulation of the cyclin D1/CDK4 pathway occurs in a majority of melanomas and increased cyclin D1/CDK4 activity (e.g. loss of p16Ink4A or Fbxo4) cooperates with BrafV600E to drive melanoma." (PMID 27977682, 2016).